CLEC4D (C-type lectin domain family 4 member D)
Diseases named in the same sentence as CLEC4D in open-access papers (continued):
Sharing a sentence is not in itself a finding about the gene and the disease.
pulmonary fibrosis (1 paper, 2024). Chronic progressive interstitial lung disorder characterized by the replacement of the lung tissue by connective tissue, leading to progressive dyspnea, respiratory failure, or right heart failure. "Finally, Clec4d and Mmp19 have been linked to pulmonary fibrosis, with Clec4d found to be highly expressed in lung tissue obtained from a mouse model of pulmonary injury and Mmp19 found to induce monocyte infiltration in human and mouse fibrotic pulmonary disease." (PMID 39056733, 2024).
cancer (67 papers, 2017 to 2026). A tumor composed of atypical neoplastic, often pleomorphic cells that invade other tissues. "In the field of cancer research, CLEC4D has garnered attention due to its potential role in tumor immunity and cancer progression." (PMID 37745724, 2023). "Negative LASSO coefficients were found for the genes KANK2 and CLEC4D that were downregulated in cancer compared with normal samples, but their log2FC was between −1 and −2." (PMID 36552262, 2022). "However, extensive research is still needed to fully understand the mechanisms of action of CLEC4D in cancer and its potential as a therapeutic target." (PMID 37745724, 2023). "A number of studies have investigated the relationship between CLEC4D and cancer." (PMID 37745724, 2023). "Additionally, the expression and function of CLEC4D may be influenced by genetic and epigenetic changes, as well as the tumor microenvironment, further suggesting its involvement in cancer through Epigenetic Clocks mediating CLEC4D expression." (PMID 37745724, 2023). "The exact mechanisms by which CLEC4D contributes to cancer development are still not fully understood, but they may involve its interactions with various ligands and complex signaling networks." (PMID 37745724, 2023).
infection (43 papers, 2013 to 2025). The state of being infected such as from the introduction of a foreign agent such as serum, vaccine, antigenic substance or organism. "In Bb-infected BMNs, DUSP1 and CLEC4D showed consistent upregulation at 1 h, 16 h, and 24 h post-infection (hpi), while Casp3 was significantly upregulated at 16 hpi and 24 hpi." (PMID 38149246, 2023). "In fact, infection with BCG led to increases in Clec4d expression on all myeloid cell populations examined, including a significant increase on alveolar macrophages." (PMID 26558717, 2016). "As the levels of Clec4d expression on pulmonary leukocytes were relatively low in naïve mice, expression of this receptor in the lung was examined following infection with M. bovis BCG." (PMID 26558717, 2016). "Clec4d (MCL) and Clec4e (Mincle) bind to Mtb ligands, (i.e., trehalose 6,6'-dimycolate, a.k.a cord factor) and are upregulated on myeloid cells after infection with other pathogens." (PMID 32544188, 2020). "Two days post intratracheal infection with BCG, there was a significant increase in total Clec4d expression on CD45+ pulmonary leukocytes compared to uninfected control mice." (PMID 26558717, 2016). "Although Dectin-1 was not essential for protection against murine infection with M. tuberculosis, CLEC4D/MCL was found to be important for murine defense against M. tuberculosis." (PMID 37446240, 2023). "In addition, we provide evidence that Clec4d and Mincle, but not Dectin‐2, are interdependently coregulated during inflammation and infection." (PMID 26558717, 2016). "Laminarin does not bind to or block CLEC4D, and thus CLEC4D is unlikely to be the PRR responsible for recognition and uptake of M. abscessus; however, these studies demonstrate the importance of extending in vitro host–pathogen interaction data to in vivo models of infection." (PMID 37446240, 2023).
tumor (34 papers, 2010 to 2025). "One possible mechanism is that CLEC4D enhances the migration, invasion, and metastasis of tumor cells by promoting epithelial-to-mesenchymal transition and activating signaling pathways involved in tumor progression." (PMID 37745724, 2023). "To further investigate the mechanism underlying the lack of response to anti-PD-1 therapy in Clec4d−/− mice, we analyzed the characteristics of the tumor-infiltrating myeloid cells for the reason that CLEC4D is mainly expressed on myeloid cells." (PMID 33963274, 2021). "Here we validated CLEC4D, a member of the CLR superfamily, was critical in mediating the immunosuppression effect of myeloid cells and in tumor resistance to anti-PD-1 therapy." (PMID 33963274, 2021). "However, the expression of CLEC4A, CLEC4D, CLEC4E, CLEC4J (FCER2), CLEC4K (CD207), CLEC4G, CLEC4H1, CLEC4M, and CLEC4H2 decreased with tumor progression." (PMID 34409028, 2021).
bacterial infections (4 papers, 2016 to 2025). "As a member of the C-type lectin receptors (CLRs) family, CLEC4D has been identified as a pivotal “sensor” on myeloid cells in the host’s defense against fungal and bacterial infections." (PMID 35957686, 2022).
CLEC4D also shares sentences with these, for which no sentence is quoted: atherosclerosis (44 papers); Salmonella Infections (20); hepatitis B (14); rheumatoid arthritis (12); Chagas disease (10); inflammatory bowel disease (10); malaria (10); legionellosis (9); prostate carcinoma (9); Yersinia infection (9); leishmaniasis (8); shigellosis (8); toxoplasmosis (8); Amoebiasis (6); colorectal cancer (6); herpesvirus infection (6); infectious disease (6); measles (6); pertussis (6); breast carcinoma (5); Candida infections (5); Epstein-Barr virus infection (5); hepatitis C (5); Insulin resistance (5); pancreatic cancer (5); alcoholic liver diseases (4); asthma (4); bladder cancer (4); cytomegalovirus infection (4); escherichia coli infection (4).
A further 85 diseases each share a sentence with CLEC4D in 4 papers or fewer.